CD14 (CD14 molecule)
Diseases named in the same sentence as CD14 in open-access papers (continued):
Sharing a sentence is not in itself a finding about the gene and the disease.
COVID-19 (continued). "In addition, CD14 and MAP4K4 were highly enriched in hydroxymethylation for patients with COVID-19 (p = 0.00033 and 0.044), and the levels of hydroxymethylation increased gradually in groups moderate, severe, and critical patients and MI." (PMID 35071229, 2021). "Even though we have not determined if the CD14+ CD3+ subset observed in our study is related to those complexes, there are associated with former COVID-19 individuals who presented immune system inflammation and dysregulation." (PMID 35069575, 2021). "Unfortunately, our study did not record when the CD14+HLA-DRlo/neg MDSC frequency of COVID-19 patients returned to normal levels." (PMID 33640878, 2021). "We found higher frequencies of neutrophils, intermediate CD14+CD16+monocytes, activated HLA-DR+CD38+, EM-like CD4+ and CD8+ T-cells in COVID-19 respiratory compared to blood samples, and similar immune responses with dexamethasone (with/without remdesivir) treatment." (PMID 34462740, 2021). "Indeed, when considering changes within each data set, M1 macrophages, plasmacytoid dendritic cells, CD14 + monocytes, CD4+ T cells, and total T cells showed change consistently in the same direction across all viral infections including COVID-19." (PMID 33437935, 2021). "In particular, the numbers of circulating classical monocytes (CD14++CD16−) decrease, but the numbers of intermediate (CD14++CD16+) and non-classical (CD14+CD16++) monocytes increase in COVID-19 patients." (PMID 34658642, 2021). "We observed a weaker induction of various cytokines and IFN-stimulated genes in CD14+ cells generated with plasma from patients with severe COVID-19 in response to poly-(I:C), whereas no such effect was observed in response to IFN-β." (PMID 34103408, 2021). "Peripheral blood was collected from critically ill, ICU patients with and without COVID-19, and CD14+ monocytes were sorted and analyzed for SETDB2." (PMID 34479991, 2021). "In analyzing single-cell transcriptomes of bronchoalveolar lavages from patients with mild and severe COVID-19, we detected the activation of the immunoproteasome component PSMB8 in the CD14+/CD16+ cell subpopulation, but these expression patterns were more muted in patients with severe COVID-19." (PMID 34225749, 2021). "In CD14+ monocytes, HIF-1 signaling may regulate LDHA, ALDOA, TIMP1, ELOB and IFNGR2, and PPAR signaling may regulate UBC, RXRA, DBI and ACSL1 in COVID-19 patients." (PMID 33936072, 2021). "We determined the frequencies of CD14+HLA-DRlo/neg MDSCs, characterized by low or negative expression of HLA-DR, in healthy controls (HCs) and COVID-19 patients." (PMID 33640878, 2021). "To test this hypothesis, we added plasma from patients with urosepsis or COVID-19 or from corresponding healthy controls, to CD34+ HSPCs or CD34+ HSPCs lacking the IL-6 receptor and observed a marked reduction in CD14+ cell production in the latter group." (PMID 34103408, 2021). "A significant expansion of CD14+CD16+ monocytes featuring high expression of IL-6 in the blood discriminated patients with COVID-19 admitted to ICUs from those who did not require intensive care." (PMID 34367190, 2021). "Interestingly, scRNA-seq unveiled a cluster of immature CD14+ monocytes, with low HLA-DR and expressing MPO, PLAC8, and IL1R2, in the blood of COVID-19 patients and similar cells were reported in sepsis." (PMID 33674591, 2021). "A single-cell RNA-sequencing analysis showed that classic CD14+ monocytes were significantly increased, whereas nonclassical CD16+ monocytes and intermediate CD14+CD16+ monocytes were remarkably reduced in the blood of COVID-19 patients with severe symptoms." (PMID 34234112, 2021). "The analyses of monocytes subpopulations including classical (CD14+CD16-), inflammatory (CD14+CD16+) and transitory (CD14lowCD16+) monocytes suggested that the percentage of inflammatory monocytes was significantly increased in COVID-19 patients compared to healthy donors." (PMID 33692788, 2021).
COVID-19 (continued). "However, in the COVID-19 patients that developed acute respiratory distress syndrome (ARDS) and required a ventilator, ACE2 was expressed in CD14 monocytes, CD8 effector T cells, dendritic cells, stem cells, and eosinophils." (PMID 34578338, 2021). "CD14+ monocytes represent the major peripheral myeloid cell type, and differential Uniform Manifold Approximation and Projection (UMAP) projection patterns of CD14+ monocytes between COVID-19 and controls indicated perturbed transcriptome features." (PMID 33101705, 2020). "At the admission time, we found a higher frequency of the PMN-MDSC cell population (identified as Lin−, HLA-DR−, CD11b+, CD33+, CD15+, CD14−) in 128 hospitalized COVID-19 patients requiring or not requiring intensive care unit (ICU) compared to HD." (PMID 33110074, 2020). "These variations suggested a trend towards a lower frequency of “classical” (CD14brightCD16-) monocytes in patients with severe COVID-19 (not significant), confirmed by the accumulation of “non-classical” – also called inflammatory – (CD14+CD16bright) monocytes in the same group (p<0.05)." (PMID 39136010, 2024). "Immunostaining of COVID-19 brains revealed extensive activation of both microglia and astrocytes, severe damage of the blood–brain barrier (BBB) and various degrees of perivascular infiltration by predominantly CD14+/CD16+/CD141+/CCR7+/CD11c+ monocytes and occasionally CD4+/CD8+ T lymphocytes." (PMID 36609561, 2023). "Moreover, COVID-19 immunophenotyping studies revealed higher levels of autophagolysosome formation in CD4+ and CD8+ cells compared to CD14+ cells (p = 0.04 and p = 0.0007, respectively); however, the autophagy level in CD19+ cells was not higher as compared to CD14+ cells." (PMID 35711451, 2022). "MicroBeads selected CD4+ T cells, CD8+ T cells, and CD14+ monocytes from PBMCs were treated with plasma exosomes from early-stage COVID-19 patients and non-COVID donors for 16 h at 37 °C, followed by flow cytometry for expression of TLR3, TLR7, TLR8, and TLR9 gating on live cells." (PMID 36526691, 2022). "Further proteome and transcriptome analyses of monocytes in patients with mild disease revealed an increase in the proportion of activated classical monocytes with the CD14+HLA-DRhiCD11hi phenotype (HLA-DRAhiCD83hi), which were absent in both the severe COVID-19 and control groups." (PMID 35632823, 2022). "In addition, several novel biomarkers for differentiating the disease severity of COVID-19 were also studied, for example, serum-neuron-specific enolase (NSE—a pulmonary injury biomarker in lung cancer), and presepsin (a soluble CD14; a proinflammatory activator of immune cells)." (PMID 35406667, 2022). "Interestingly, a similar decrease in the CD14+CD16– subset was observed in non-obese individuals with severe COVID-19 and type 2 diabetes." (PMID 36687421, 2022). "However, the small numbers of CD34 + cells in the PBMC fraction of COVID-19 patients and the lack of CD14 + cells in this subset suggest no interference with our results for CD14 + CD15- cells, isolated with our method." (PMID 36443794, 2022). "Likewise, CD14++CD16- classical and CD14+CD16+ non-classical monocytes lost their ability to produce IFN-alpha in response to polyclonal stimuli in participants who developed severe COVID-19 compared to mild cases." (PMID 35860236, 2022). "Indeed, levels of soluble CD14 (sCD14; monocyte inflammation marker) and myeloperoxidase (MPO; neutrophil inflammation marker) were significantly higher during severe COVID-19 compared to mild and control groups." (PMID 34177935, 2021). "Although overproduction of IL-6 mediates the low HLA-DR expression on CD14+ monocytes of patients with severe COVID-19, anti-IL6 therapy has been unsuccessful in showing improved outcomes in COVID-19, highlighting the urgent need for elucidating the underlying mechanisms." (PMID 33765435, 2021).
COVID-19 (continued). "We found that CD14+ monocytes from patients positive for COVID-19 demonstrated significantly reduced expression of SETDB2 compared to other critically ill ICU patients without COVID-19 and to healthy donors." (PMID 34479991, 2021). "Indeed, in COVID-19 patients the number of CD14+ cells lacking HLADR is increased and remains so through the course of the disease." (PMID 34149697, 2021). "Thus, our data revealed that the proportion of CD14+ monocytes begins to expand in the early stage of severe patients, and the CD14+/CD16+ monocyte ratios can serve as an appropriate early prognostic marker for severe COVID-19." (PMID 35095917, 2021). "An excessively activated immune response could be caused by pathogenic GM-CSF+Th1 cells and by the induced or inflammatory CD14+ CD16+ monocytes/macrophages, which play an important role in pulmonary immunopathology and systemic inflammatory reaction in patients with COVID-19." (PMID 32722596, 2020). "Interestingly, CD14+CD162+ (non-classical) monocytes were hardly detectable in COVID-19 patients, which corroborates recent reports by others." (PMID 33377122, 2020). "Unlike MCEMP1, which was exclusively differentially expressed in CD14+ cells, reduced expression of HLA-DRA could be detected more broadly across other myeloid cells, B cells, T cells, NK cells and platelets, indicating a global suppression of antigen presentation in severe COVID-19 patients." (PMID 36801619, 2023). "SARS-CoV-2 protein-expressing circulating monocytes might be directly related to prolonged inflammation, severity, and the long-term phase of COVID-19, since studies revealed the increase of intermediate (CD14+CD16+) and nonclassical (CD14loCD16+) monocytes in COVID-19." (PMID 36634048, 2023). "Another study of COVID-19 patients found a negative correlation between the serum concentration of IL-6 and the level of HLA-DR expression on the CD14+ monocytes, as well as between the total number of lymphocytes and the absolute number of HLA-DR mRNA isolated from CD14+ monocytes." (PMID 35632823, 2022). "Furthermore, in comparison to mildly infected patients, severe COVID-19 patients showed an increase in the populations of the highly inflammatory monocyte-derived FCN1+ macrophages in their Broncho Alveolar Lavage Fluid (BALF) and the CD14+CD16+ inflammatory monocytes in their peripheral blood." (PMID 35062368, 2022). "Interestingly, the frequency of CD14+HLA-DRlo/neg MDSCs showed negative correlation to lymphocyte counts, suggesting that MDSCs may be involved in the lymphopenia detected in COVID-19." (PMID 33640878, 2021). "However, it increased expression levels of alarmins S100A12 and S100A9, and it decreased the expression of MHCII and ENTPD1 of CD14+ monocytes, suggesting that persistent levels of SPP1 may contribute to long–COVID-19 pathologies by skewing monocytes toward a proinflammatory phenotype." (PMID 34143756, 2021). "Significantly, the hyperinflammatory subtype of monocytes express CD14 and CCL3, which broadly express more cell-type-specific cytokines, and this might be one of the major sources in PBMCs triggering the inflammatory cytokine storm in severe COVID-19 patients." (PMID 34975921, 2021). "Specifically, the frequency of peripheral NK cells, the expression of PD-L1 on CD14+ monocytes, and TREM-1 on CD11b+ HD neutrophils were the major discriminators between OB and N-OB patients with severe COVID-19, regardless of age and sex." (PMID 37626613, 2023). "COVID-19 plasma exosomes induced proinflammatory responses in CD4+ T cells, CD8+ T cells, and CD14+ monocytes but not significantly in regulatory T cells, Th17 T cells, or central memory T cells." (PMID 36526691, 2022). "For example, in patients with COVID-19, the number of CD14++CD16− T lymphocytes is typically low, while CD14++CD16+ (intermediate) and CD14+CD16++ (non-classical) monocytes increase." (PMID 35466278, 2022).
COVID-19 (continued). "CD14− DC3s (CR1: 22; CR2: 21) and CD14+ DC3s (CR1: 11) differ between individuals recovered from non-severe and severe COVID-19 in agreement with our manual analysis." (PMID 36433939, 2022). "In peripheral blood, acute COVID-19 patients show a decrease of non-classical (CD14−CD16+) and an increase of intermediate (CD14+CD16+) monocytes." (PMID 34572439, 2021). "In the COVID-19 patients who did not require a ventilator, ACE2 was expressed in CD14 monocytes, CD4 memory and naive T cells, and dendritic cells; TMPRSS2 was expressed in several immune cells." (PMID 34578338, 2021). "Of interest, a decrease in CD14+CD16- classical monocytes was detected in COVID-19 patients with respect to the other two groups, but no changes were noticed in the levels of CD14+CD16+ intermediate and CD14dimCD16+ non-classical monocytes between COVID-19 patients and healthy blood donors." (PMID 34944610, 2021). "Other studies, instead, reported that the number of CD14highCD16- classical monocytes is decreased in COVID-19 patients, while the abundance of inflammatory CD14+CD16+, CD14highCD16+ intermediate, and CD14+CD16high nonclassical monocytes increased according to the severity of COVID-19." (PMID 34209845, 2021). "For example, it was found that the number of monocytes of patients with severe COVID-19 decreased, particularly of classical monocytes (CD14++CD16-), and that nonclassical monocytes (CD14+CD16++) significantly depleted in samples from COVID-19 patients with ARDS." (PMID 33390810, 2021). "expansion of nonclassical (CD14−, CD16+) and intermediate (CD14+, CD16+) monocyte subsets– may correlate with COVID-19 severity and clinical outcome." (PMID 34135448, 2021). "In PBMCs isolated from individuals vaccinated for COVID-19, there was no change in the proportion of ACE2+ or ACE2me+ cells pre- and post-vaccination, but the expression intensity of ACE2me was significantly higher in PBMCs and CD14+ monocytes from vaccinated individuals." (PMID 37369668, 2023).
Sepsis (244 papers, 2006 to 2026). Sepsis is defined as life-threatening organ dysfunction caused by a dysregulated host response to infection. "HLA DR on CD14+ monocyte is associated with several diseases, including sepsis and coronary atherosclerosis." (PMID 41446630, 2025). "Recent studies have shown that soluble CD14 isoforms (presepsin) have diagnostic and prognostic values in sepsis." (PMID 40124361, 2025). "By combining these two analytical methods, we found that the low expression of LGALS9 in sepsis patients is associated with the activation and differentiation of CD14+ monocytes and CD4+‐naive T cells." (PMID 39044269, 2024). "Recent research showed that soluble CD14, known as presepsin, has diagnostic value for pediatric sepsis patients." (PMID 40626122, 2024). "MAGICAL identified sepsis-associated regulatory circuits predominantly in CD14 monocytes, known to be activated by bacterial sepsis." (PMID 37974651, 2023). "While we didn’t find any variants of IL1RN or CD14 to be associated with sepsis, we found two variants of tissue factor pathway inhibitor (TFPI), an anticoagulant protein, to be associated with Sepsis-2, but not Sepsis-3." (PMID 35275946, 2022). "In summary, increasing pro-inflammation with the transition of sepsis to septic shock appears to be associated with lower CD14+ and CD33+ and up-regulation of CD16, particularly in obese patients." (PMID 36687421, 2022). "PSEP, a soluble CD14 protein, is a highly accurate predictor of sepsis according to the Sepsis-3 criteria, and it has good diagnostic accuracy for bacteremia and candidemia, including the IC." (PMID 35330311, 2022). "Both CD11b and CD14 are associated with unsatisfactory results in follow-up and monitoring evaluations of sepsis patients." (PMID 34691286, 2021). "CD14 is a transmembrane protein present in many cells implicated in the sepsis cascades, including macrophages, monocytes, and granulocyte cells which is responsible for the intracellular transduction of endotoxin signals." (PMID 34150378, 2021). "Yet, it remained unclear what causes this rise in CD14 and what role this molecule plays in the development of sepsis." (PMID 33135636, 2020). "The glucocorticoid (GC) treatment was often used in controlling sepsis, which was associated with the downregulation of CD14 production in monocytes and macrophage." (PMID 31312662, 2019). "In order to understand the severity of immunosuppression in cancer patients, we compared the presence of CD14+HLA-DRlo/neg monocytes in cancer patients to those patients with acute lung injury with or at risk for sepsis." (PMID 31191529, 2019). "This underlines the probable role of CD14 rs2569190 polymorphism on the other sepsis types, but further analysis with bigger sample size would be needed to corroborate such association." (PMID 29426837, 2018). "To date, discrepant results have been described for the association between CD14 rs2569190 polymorphism and sepsis and death." (PMID 29426837, 2018). "This meta-analysis mainly focused on the associations between CD14-159C/T polymorphism and susceptibility to sepsis or sepsis-related mortality." (PMID 28122493, 2017). "Ten studies that evaluated the effect of the CD14 polymorphisms on incidence of sepsis were ultimately analyzed in our meta-analysis, as well as nine studies that demonstrated the effect of the CD14 polymorphisms on sepsis-related mortality." (PMID 28122493, 2017). "A total of 14 studies for the association between CD14 polymorphism and sepsis were included in the final meta-analysis." (PMID 28122493, 2017). "Subgroup analysis among Asian population illustrated that the T allele and the CD14-159 TT genotype was related to susceptibility to sepsis." (PMID 28122493, 2017). "On one hand, the study investigated relations between CD14-159C/T polymorphism and susceptibility to sepsis." (PMID 28122493, 2017).